COMT (catechol-O-methyltransferase)
Diseases named in the same sentence as COMT in open-access papers (continued):
Sharing a sentence is not in itself a finding about the gene and the disease.
cognitive decline (30 papers, 2009 to 2025). "We show that HD gene carriers with fewer CAG repeats and with the Val allele in COMT polymorphism displayed slower cognitive decline." (PMID 27657697, 2016). "The Val allele is associated with higher COMT enzyme availability and has previously been associated with cognitive decline, although findings were mixed." (PMID 26973509, 2016). "Indeed, COMT gene variants that alter dopamine levels are associated with cognitive decline in PD and, similarly, impaired cognitive flexibility following TBI." (PMID 38611750, 2024). "This link, which was more pronounced among individuals with low dopamine levels (i.e., COMT any Val carriers), may indicate an early marker for oncoming cognitive decline among Val carriers, underlining the importance of further investigation." (PMID 35571998, 2022). "Other side-effects such as cognitive decline, visual hallucinations and daytime sleepiness have been implicated in various polymorphisms of the COMT, DRD2, DRD3, HOMER1 and BDNF genes, but lack consistency in the results to consider current clinical implementations." (PMID 34281267, 2021). "Thus far, the role of COMT in the pathogenesis of AD has mainly been focused on the association between its most commonly investigated functional polymorphism, Val158/108Met, and the development of AD and/or cognitive decline." (PMID 36830773, 2023). "Because previous work has illustrated that the effects of COMT may emerge in older adults and individuals at risk for cognitive decline, we performed a secondary analysis, excluding the younger age cohorts while controlling for demographic factors and retest effects." (PMID 26973509, 2016). "Specifically, polymorphisms affecting the MAPT, COMT, GBA, and APOE genotypes have been linked to cognitive decline." (PMID 37885554, 2023). "Six genes were associated with frailty and cognitive decline in Sargent’s recent review: IL-6 rs1800796, TNF rs1800629, IL-18 rs360722, IL1-beta rs16944, and COMT rs4680 for cognitive decline and COMT rs4646316 for frailty." (PMID 32257550, 2020). "The genes selected for investigation included genetic polymorphisms with well-described influences on cognitive function, brain plasticity, and risk of ageing-related cognitive decline (APOE, BDNF Val66Met, KIBRA, COMT Val158Met, SERT 5-HTTLPR)." (PMID 30631459, 2017). "The link between COMT gene variation and cognitive performance at different stages of the illness suggests that genetic factors may contribute to cognitive decline as the disease progresses." (PMID 39518545, 2024). "Other genes such as glucocerebrosidase (GBA), microtubule-associated protein tau (MAPT), and catechol O-methyltransferase (COMT), may also be associated with cognitive decline in PD." (PMID 38988604, 2024). "For example, the Catechol-O-methyltransferase genotype was found to be related to executive-attention function, and the apolipoprotein E genotype is related to cognitive decline, especially the posterior cortical dysfunction, in the PD population." (PMID 36147702, 2022). "The metabolism of levodopa down the COMT pathway has been speculated to result in the saturation of cellular methylation capacity in Parkinson's disease (PD) and in accelerated cognitive decline and dementia." (PMID 19793392, 2009). "Additionally, we focus on the role of polymorphisms within the genes for catechol-O-methyltransferase (COMT), apolipoprotein E (APOE), vascular endothelial growth factor (VEGF), and for renin-angiotensin-aldosterone system components, and their contribution to cognitive decline in PD." (PMID 33802165, 2021). "It is tempting to speculate that genes such as PIK4CA and SNAP29 that are deleted in our patient may be involved in the emergence of psychotic "positive symptoms" while others, such as PRODH and COMT that are not deleted, play a role in the cognitive decline process." (PMID 23245648, 2012).
Dyskinesia (28 papers, 2012 to 2025). A movement disorder which consists of effects including diminished voluntary movements and the presence of involuntary movements. "For instance, one study reported an increased susceptibility to LD-induced dyskinesia in Brazilian PD carriers of COMT Met/Met, with similar trends observed in Japanese patients with PD." (PMID 39338193, 2024). "Some studies showed that PD patients with high COMT activity require higher levodopa doses and are at and lower risk of levodopa-induced dyskinesia, compared to the PD patients with low COMT activity." (PMID 36337703, 2022). "Some of the PD-related susceptibility genes have been also associated with levodopa-induced motor complications in PD patients; for instance, polymorphisms in MAO-B and COMT genes have been shown to increase the risk of developing dyskinesias and wearing-off." (PMID 35203939, 2022). "Subsequently, an increasing number of studies have been performed to determine the association between the COMT rs4680 polymorphism and PD, including those investigating susceptibility, age of onset and dyskinesia." (PMID 32533012, 2020). "The most studied COMT SNP rs4680 has already been associated with motor fluctuations, dyskinesia, and daytime sleepiness." (PMID 30745869, 2019). "Additionally, genotype differences in COMT variants rs165728 or rs174699 have been associated with variations in LD dosage and susceptibility to dyskinesia in Chinese patients with PD." (PMID 39338193, 2024). "Excluding the hepatic concern, the safety profile of tolcapone can be considered comparable to other COMT inhibitors, including a low drop-out rate for dyskinesia, being the most frequent cause of treatment discontinuation in patients under opicapone 50 mg/day." (PMID 33415500, 2021). "Although the variations in COMT enzymatic activity on the onset of adverse events is still under debate, several studies have linked the lower COMT enzymatic activity to the increased incidence of motor complications such as dyskinesia, especially in advanced PD." (PMID 34281267, 2021). "Hypothetically, more moderate COMT enzymatic activity could lead to inadequate dopamine inactivation and the accumulation of dopamine in the synaptic cleft, thereby causing the dyskinesias." (PMID 34281267, 2021). "Our primary results showed the possible association of SNPs other than the most common functional rs4680 in COMT with interindividual variance in the L-dopa daily dose and susceptibility to dyskinesia in Chinese patients, although this was an exploratory study based on a small sample size." (PMID 32533012, 2020). "In addition to the “wearing-off” phenomenon, a recent prospective study showed that the homozygosity in the AA allele of the COMT Val158Met polymorphism increases the risk of dyskinesia, which also suggests that the AA genotype may decrease L-dopa metabolism." (PMID 28451382, 2017). "How effective is the additional administration of COMT inhibitors or dopamine agonists compared to placebo in the treatment of patients with advanced PD with dyskinesias?" (PMID 39207521, 2024). "The literature discussed in depth the temporal relationship between different antiparkinsonian drugs and dyskinesias, highlighting the major role played by levodopa over dopamine agonists, COMT inhibitors and MAO inhibitors." (PMID 37445461, 2023). "It persists an ongoing dilemma regarding COMT inhibitor use when choosing between potential improvement in wearing off and the risks of worsening of dyskinesia or occurrence of intolerable gastrointestinal effects." (PMID 34942868, 2021). "The last three along with COMT rs165815, and NOS1 rs2293054 were associated with time to occurrence of dyskinesia within the clinical-pharmacogenetic model." (PMID 31156712, 2019).
Dyskinesia (continued). "One study in Poland reported a high frequency of patients with late onset PD who were carriers of the G_C_G_G (high activity) haplotype, and the COMT haplotype seemed to have little influence on the development of levodopa-induced dyskinesia." (PMID 28451382, 2017). "COMT inhibitors dopaminergic side effects include dyskinesia, hypotension, and nausea." (PMID 35010624, 2021). "In contrast with our non-significant findings, COMT rs4680 was associated with the occurrence of dyskinesia, motor fluctuations, and daytime sleepiness in other studies." (PMID 30745869, 2019). "When patients experience wearing-off, the dose or number of administrations of levodopa may be adjusted, or levodopa adjunctive drugs such as a dopamine agonist (DA), monoamine oxidase B (MAO-B) inhibitor, or catechol-O-methyltransferase (COMT) inhibitor are added to avoid dyskinesia." (PMID 40529448, 2025). "COMT rs165815 has also never been associated with dyskinesia, which is similar to the case of MF." (PMID 31156712, 2019). "It was reported in recent years that several genetic variations (such as COMT Val158Met, BDNF val66met, mu opioid receptor polymorphism and dopamine D2 receptor intronic dinucleotide repeat polymorphism) were associated with the occurrence of motor complications, especially for dyskinesia." (PMID 25671102, 2014). "These assessments can be confounded by the effects of symptomatic medications, such as the involuntary dyskinesias induced by Levodopa, dopamine agonists, MAO-B inhibitors, and COMT (catechol-o-methyltransferase) inhibitors." (PMID 40588759, 2025). "On this basis, when treating patients showing extensive motor fluctuations including dyskinesias before STN-DBS implantation, postoperative continuation of COMT inhibition by opicapone should be considered for stabilisation of the dopaminergic stimulation." (PMID 39429501, 2024). "COMT inhibitors and MAO-B inhibitors were usually used as the adjunct therapy to levodopa or dopamine agonists in reducing motor complications such as dyskinesia and their use has resulted in the reduction of the dose of levodopa when used in combination." (PMID 35010624, 2021). "Besides, low doses of levodopa in combination with COMT inhibitors may prevent dyskinesia." (PMID 35010624, 2021). "An experimental animal trial showed lower frequency and less intensity of dyskinesia, when a treatment with LD/DDI with the COMT inhibitor EN, given four times daily, was started right from the beginning." (PMID 23211041, 2012). "Addition of COMT-inhibitors to a LD/DDI regimen without concomitant individual adaption of LD/DDI intake by extension of dosing intervals or reduction of LD/DDI dosage may induce dyskinesia." (PMID 23211041, 2012).
dementia (22 papers, 2009 to 2025). Loss of intellectual abilities interfering with an individual's social and occupational functions. "COMT affects cognitive control and functions in humans, and it is linked to the development of dementia." (PMID 36830773, 2023). "These may include factors already associated with cognitive dysfunction and dementia in other populations, such as apolipoprotein E, complement receptor 1, clusterin, sortilin-related receptor 1, catechol-O-methyltransferase and BDNF." (PMID 40235626, 2025). "In 2019, a study investigated the association of single nucleotide polymorphisms in a few genes, including COMT, with the pathogenesis of AD and risk of dementia in 2857 postmenopausal women over the age of 65 years from the Women’s Health Initiative Memory Study (WHIMS)." (PMID 34725583, 2021). "The results showed that the COMT gene was associated with probable dementia and that the studies involving candidate genes might help discover new pathways of structural and functional aging of the brain and understand variations in structure and function of the brain of different individuals." (PMID 34725583, 2021). "Our results also validate those reported in normal elderly and in patients with dementia in that those with low COMT enzyme activity perform better in prefrontal-directed tasks or that it is related to psychiatric manifestations." (PMID 28707072, 2018). "Williams-Gray and coworkers have found that the frontal type deficits at the early stages of disease are not related to dementia at follow-up but to COMT gene mutations, that is, to dopamine dysfunction." (PMID 24303226, 2013). "Thus, Bifidobacterium was likely to be increased by COMT inhibitors and decreased by dementia." (PMID 36494405, 2022). "The authors provided evidence of the generation of homocysteine through levodopa metabolism by catechol-O-methyltransferase (COMT) and its involvement in dementia." (PMID 40137172, 2025). "However, both BDNF and COMT have been reported as playing indirect or complementary roles in some studies with implications for MCI and dementia." (PMID 25249975, 2014). "Earlier detection would facilitate therapy, and this is precisely why the goal of this research was to determine whether a reliable biomarker for the development of dementia can be established through the expression and methylation of BDNF and COMT in peripheral blood." (PMID 36830773, 2023). "At present, the absence of COMT from the pantheon of MCI-related genes may be associated with the fact that, by the time individuals convert to dementia, the genetic associations are overwhelmed by APOE and its direct connection to amyloid beta deposition." (PMID 25249975, 2014). "The nonsignificant reductions in dementia and mortality among those who received MAO-B inhibitors compared with COMT inhibitors add support for this possibility, and no safety concerns were observed among those receiving MAO-B inhibitors." (PMID 34962574, 2022).
fibromyalgia (22 papers, 2006 to 2025). A chronic disorder of unknown etiology characterized by pain, stiffness, and tenderness in the muscles of neck, shoulders, back, hips, arms, and legs. "The insights into fibromyalgia's genetic basis, particularly from studies on COMT, serotonin transporter, and dopamine receptor polymorphisms, provide a strong foundation for understanding individual susceptibility to fibromyalgia." (PMID 40291383, 2025). "Genetic predispositions in CYP2D6 and catechol-O-methyltransferase contribute to high pain sensitivity and analgesic therapy failure in a fibromyalgia patient, suggesting the need for further study." (PMID 39995492, 2025). "Recent findings have associated different COMT genotypes with working memory capacity in patients with fibromyalgia." (PMID 36100778, 2023). "Allele and genotype frequencies of COMT in the patients with fibromyalgia and the healthy controls participants." (PMID 33909692, 2021). "More recently, a meta-analysis conducted by Lee and colleagues (2015) revealed that patients with fibromyalgia carrying the Met allele of COMT (Met/Met + Val/Met genotypes) showed a higher impact of the disease than those carrying the Val allele." (PMID 33909692, 2021). "Further investigations have confirmed the relationship between COMT polymorphism and pain catastrophizing in patients with fibromyalgia." (PMID 33909692, 2021). "We identified, for the first time, associations of the rs841 (guanosine triphosphate cyclohydrolase 1 gene) and rs2097903 (catechol-O-methyltransferase gene) SNPs with higher risk of fibromyalgia susceptibility." (PMID 29486785, 2018). "In conclusion, we identified associations of the rs841 (GCH1 gene) and rs2097903 (COMT gene) SNPs with higher risk of fibromyalgia." (PMID 29486785, 2018). "We identified, for the first time, that the rs841 (GCH1 gene) and rs2097903 (COMT gene) SNPs were associated with having fibromyalgia." (PMID 29486785, 2018). "The association between COMT single nucleotide polymorphisms (SNPs) and fibromyalgia susceptibility is controversial." (PMID 29486785, 2018). "Studies examining the association between COMT and fibromyalgia have largely focused on a single functional polymorphism, rs4680 or val158met, which reduces enzymatic activity by 3- to 4-fold, and is associated with an increased risk of chronic pain." (PMID 30886988, 2018). "In line with our data of lower IgG3 levels in CFS patients with the Met/Met genotype of COMT in patients with fibromyalgia this COMT variant was shown to be associated with lower salivary IgA concentration." (PMID 26272340, 2015). "Further, in fibromyalgia enhanced pain sensitivity was reported for patients with this COMT variant." (PMID 26272340, 2015). "Previously, individuals with the COMT Val/Val genotype have been found to be less susceptible to pain, and in one study fibromyalgia was less frequent among those with the Val/Val genotype." (PMID 16674809, 2006). "Genetic testing for COMT variants may help identify individuals at increased risk for fibromyalgia or those who may benefit from specific therapeutic approaches targeting the dopaminergic system." (PMID 40291383, 2025). "Catechol-O-methyltransferase (COMT) gene is one of the possible candidates associated, at least partially, with inter-individual variability in physical, psychological or cognitive symptoms in fibromyalgia." (PMID 36100778, 2023). "In summary, present results suggest that COMT gene might influence ERP activity associated with working memory processing in fibromyalgia patients." (PMID 36100778, 2023). "The present results indicate that different genotypes of the Val158Met COMT polymorphism might contribute to the individual differences related to fatigue symptoms in fibromyalgia syndrome." (PMID 33909692, 2021).